Y_RNA (Y RNA )
Gene: Miscellaneous RNA gene on chromosome 7 (115,833,273 to 115,833,373, reverse strand). Ensembl gene ENSG00000199224.
Homologues: Orthologues: chimpanzee Y_RNA (99% identical), macaque Y_RNA (89% identical). Paralogues in human: Y_RNA (88% identical), RNY3 (87% identical), Y_RNA (87% identical), Y_RNA (86% identical), RNY3P1 (85% identical), Y_RNA (85% identical), Y_RNA (84% identical), RNY3P16 (83% identical), Y_RNA (83% identical), RNY3P13 (82% identical), RNY3P2 (82% identical), RNY3P9 (82% identical), and 92 more.